RPL6 (ribosomal protein L6)
Description:
Component of the large ribosomal subunit. The ribosome is a large ribonucleoprotein complex responsible for the synthesis of proteins in the cell. (Microbial infection) Specifically binds to domain C of the Tax-responsive enhancer element in the long terminal repeat of HTLV-I.
Synonyms: TaxREB107; TXREB1; L6; eL6; SHUJUN-2
Tractability: Small molecule: an approved drug acts on it; a structure with a bound ligand is known; a high-quality ligand is known. PROTAC: UniProt records ubiquitination sites on it; ubiquitination databases record sites on it; its protein half-life has been measured; a small molecule that binds it is known. Other modalities: a drug acting on it is in phase 2 or 3 trials.
Target class: Other cytosolic protein
Gene: Protein-coding gene on chromosome 12 (112,405,170 to 112,418,844, reverse strand). Ensembl gene ENSG00000089009.
Subcellular location: Cytoplasm, cytosol; Cytoplasm; Rough endoplasmic reticulum
Pathways (Reactome):
Metabolism of proteins: Eukaryotic Translation Termination; Formation of a pool of free 40S subunits; GTP hydrolysis and joining of the 60S ribosomal subunit; L13a-mediated translational silencing of Ceruloplasmin expression; PELO:HBS1L and ABCE1 dissociate a ribosome on a non-stop mRNA; Peptide chain elongation; Ribosome Quality Control (RQC) complex extracts and degrades nascent peptide; SRP-dependent cotranslational protein targeting to membrane; ZNF598 and the Ribosome-associated Quality Trigger (RQT) complex dissociate a ribosome stalled on a no-go mRNA
Metabolism of RNA: Major pathway of rRNA processing in the nucleolus and cytosol; Nonsense Mediated Decay (NMD) enhanced by the Exon Junction Complex (EJC); Nonsense Mediated Decay (NMD) independent of the Exon Junction Complex (EJC)
Cellular responses to stimuli: Response of EIF2AK4 (GCN2) to amino acid deficiency
Developmental Biology: Regulation of expression of SLITs and ROBOs
Disease: Viral mRNA Translation
Metabolism: Selenocysteine synthesis
Gene Ontology:
Molecular function: cadherin binding; protein binding; RNA binding; structural constituent of ribosome; DNA binding
Biological process: cytoplasmic translation; negative regulation of myoblast fusion; regulation of DNA-templated transcription; spermatogenesis; striated muscle contraction; translation
Cellular component: cytoplasmic ribonucleoprotein granule; cytosolic large ribosomal subunit; cytosolic ribosome; focal adhesion; membrane; nucleus; cytoplasm; cytosol; rough endoplasmic reticulum; large ribosomal subunit; postsynaptic density; ribosome; synapse
Genetic constraint (gnomAD): Loss-of-function variants: 1 observed, 27.01 expected, observed/expected ratio (o/e) 0.037, 90% interval 0.012 to 0.18. The upper end of that interval is the gene's LOEUF score, 0.18, which puts it in group 1 of 6, group 1 being the genes least tolerant of losing a copy. Missense variants: 248 observed, 308.35 expected, observed/expected ratio (o/e) 0.8, 90% interval 0.72 to 0.89. Synonymous variants: 105 observed, 113.09 expected, observed/expected ratio (o/e) 0.93, 90% interval 0.79 to 1.09.
Homologues: Orthologues: chimpanzee RPL6 (100% identical), guinea pig RPL6 (93% identical), pig RPL6 (92% identical), rabbit RPL6 (91% identical), mouse Rpl6 (89% identical), tropical clawed frog rpl6 (73% identical), zebrafish rpl6 (70% identical), Drosophila melanogaster RpL6 (47% identical), Caenorhabditis elegans rpl-6 (38% identical).